NCOA4 (nuclear receptor coactivator 4)
Diseases named in the same sentence as NCOA4 in open-access papers (continued):
Sharing a sentence is not in itself a finding about the gene and the disease.
Stroke (5 papers, 2020 to 2025). Sudden impairment of blood flow to a part of the brain due to occlusion or rupture of an artery to the brain. "This work not only delineates the NCOA4-ferritinophagy-ferroptosis axis but also identifies the USP14-NCOA4 interaction as a novel therapeutic target for stroke." (PMID 40529211, 2025). "Ferroptosis, an autophagic cell death process, leads to autophagy activation and consequent ferritin and NCOA4 degradation, and NCOA4-regulated ferritinophagy maintains ferroptosis via mediating cellular iron homeostasis, which is also present in stroke." (PMID 35264947, 2021). "In this study, we analyzed the expression of DUSP1, NCOA4 and SLC2A3 at 3, 5 and 24 h after stroke based on the GSE58294 dataset." (PMID 37699956, 2023).
cervical cancer (4 papers, 2023 to 2024). A primary or metastatic malignant neoplasm involving the cervix. "Furthermore, dihydroartemisinin (DHA) induces NCOA4-mediated ferritinophagy in cervical cancer, leading to increased labile iron pool (LIP), enhanced Fenton reaction, and excessive ROS production, triggering ferroptosis, and sensitizing cervical cancer cells to doxorubicin." (PMID 39045454, 2024). "Moreover, nuclear receptor coactivator 4 (NCOA4)-mediated ferritinophagy was also induced by DHA leading to subsequent increases of intracellular labile iron pool (LIP), exacerbated the Fenton reaction resulting in excessive ROS production, and enhanced cervical cancer ferroptosis." (PMID 37065442, 2023).
chronic obstructive pulmonary disease (4 papers, 2020 to 2024). A chronic and progressive lung disorder characterized by the loss of elasticity of the bronchial tree and the air sacs, destruction of the air sacs wall, thickening of the bronchial wall, and mucous accumulation in the bronchial tree. "Ferritin degradation via NCOA4-mediated ferritinophagy had been responsible for ferroptosis of bronchial cells in chronic obstructive pulmonary disease (COPD) and in LPS-induced H9c2 myofibroblasts." (PMID 38463857, 2024). "Immunohistochemistry of lung tissue also showed enhanced expression of NCOA4 in bronchial epithelial cells of chronic obstructive pulmonary disease patients." (PMID 36060261, 2022). "In chronic obstructive pulmonary disease pathogenesis, NCOA4-mediated ferritinophagy is initiated during ferritin degradation in response to cigarette smoke-induced epithelial cell ferroptosis." (PMID 33632938, 2021). "NCOA4 expression levels are significantly higher in lung homogenates from chronic obstructive pulmonary disease patients than non-smokers and non-chronic obstructive pulmonary disease smokers." (PMID 36060261, 2022).
gastric cancer (4 papers, 2020 to 2025). A primary or metastatic malignant neoplasm involving the stomach. "Similarly, gastric cancer resists ferroptosis via the PLAGL2-STAU1-NCOA4 axis, where STAU1 destabilizes NCOA4 mRNA, suppressing ferritinophagy and reactive iron accumulation." (PMID 40919170, 2025). "Lenvatinib targets NCOA4 in COAD; this drug is known to reduce tumor growth, and it is tested in phase 2 clinical trials to treat gastric cancer patients." (PMID 33670487, 2021).
virus infection (4 papers, 2024 to 2025). "We further examined the viral titers in the supernatants of NCOA4 KO and WT cells after viral infection, which were consistent with the western blotting results that NCOA4 KO significantly inhibited PR8 H1N1 viral replication." (PMID 39159143, 2024). "Besides confirming FTH as an established NCOA4 target, we now provide evidence that FtMt is also under the control of NCOA4 during virus infection." (PMID 38226812, 2024). "In addition to confirming FTH as an established target of NCOA4, we now provide evidence that NCOA4 also regulates FTMT during virus infection." (PMID 40197059, 2025). "However, in the virus-infected mock cells, the mRNA levels of NCOA4, ACSL4, and STEAP3 considerably increased while being down-regulated in the DDX3X-silenced cells with virus infection." (PMID 39155369, 2024).
cardiac hypertrophy (3 papers, 2021 to 2024). "Taken together, NCOA4 deficiency attenuated pressure overload-induced cardiac remodeling, including cardiac hypertrophy and dysfunction, chamber dilation, and fibrosis." (PMID 33526170, 2021). "Increasing evidence substantiates the effect of NCOA4‐mediated ferritnophagy on human diseases, such as neurodegenerative disorders, cardiac hypertrophy, inflammatory‐related diseases and cancer." (PMID 38389491, 2024). "This indicates that NCOA4 functions upstream of SFXN1 and implicates NCOA4-mediated autophagy and ferroptosis in the development of cardiac hypertrophy." (PMID 38102663, 2023). "Apelin-13-induced mitochondrial iron excess is reversed by inhibiting SFXN1 and NCOA4 expression, which it also mitigates cardiac hypertrophy." (PMID 38102663, 2023). "Recently, evolving studies have documented that NCOA4‐mediated ferritinophagy plays a central role in ferroptosis initiation and drives significant pathological processes in cardiovascular diseases, such as heart failure (HF), cardiac hypertrophy and cardiac ischaemia/reperfusion (I/R) injury." (PMID 38389491, 2024).
cholangiocarcinoma (3 papers, 2017 to 2025). A carcinoma that arises from the intrahepatic biliary tree (intrahepatic cholangiocarcinoma) or from the junction, or adjacent to the junction, of the right and left hepatic ducts (hilar cholangiocarcinoma). "The investigators speculated whether NCOA4 is involved in the development of cholangiocarcinoma through the mechanism underlying GPX4-mediated iron-dependent cell death." (PMID 40788949, 2025). "The 5-year prognostic survival rate of patients with cholangiocarcinoma with low NCOA4 expression was significantly lower than that of patients with high NCOA4 expression." (PMID 40788949, 2025). "In cancers such as cholangiocarcinoma, colon adenocarcinoma, and glioma, NCOA4 is expressed at low levels, and the overall survival of patients is reduced." (PMID 40788949, 2025). "The results revealed that NCOA4 expression was significantly lower in cholangiocarcinoma tumor samples compared to normal tissues." (PMID 40788949, 2025). "This indicates that NCOA4 has a significant impact on the survival prognosis of patients with cholangiocarcinoma." (PMID 40788949, 2025). "Among the 12 clinical specimens we collected, cholangiocarcinoma tissues had significantly lower NCOA4 expression than paraneoplastic tissues." (PMID 40788949, 2025). "This suggests that a low expression of NCOA4 is likely to promote the malignant development of cholangiocarcinoma." (PMID 40788949, 2025). "In this study, we selected cholangiocarcinoma cells and used gene silencing to downregulate NCOA4 expression in cells to investigate its effect on the proliferation, metastasis, and invasive ability of cholangiocarcinoma cells and identify the potential mechanism of ferroptosis." (PMID 40788949, 2025). "However, a major shortcoming of this study was that the collection of cholangiocarcinoma tissue specimens is challenging, and the sample size is considerably small to fully account for the differences in NCOA4 expression." (PMID 40788949, 2025). "Moreover, the frequency of modifications (>5%) in NCOA4 “structural variation” and “amplification” in cholangiocarcinoma was the greatest kind." (PMID 35756082, 2022). "Furthermore, the frequency of modifications (>5%) in NCOA4 “structural variation” and “amplification” in cholangiocarcinoma was the greatest kind." (PMID 35756082, 2022). "In this study, the expression of NCOA4 and GPX4 in cholangiocarcinoma cells confirmed the presence of iron-mediated cell death in cholangiocarcinoma cells and its involvement in cellular regulation." (PMID 40788949, 2025). "The experimental results of this study illustrate that NCOA4 knockdown increases GPX4 expression, inhibits iron-mediated cell death, and promotes the malignant behavior of cholangiocarcinoma cells." (PMID 40788949, 2025). "Examining cholangiocarcinoma, we observed that the HRAS, KIT, ZBTB16, FAS and NCOA4 genes were altered by high methylation (shown in light sea green)." (PMID 28178311, 2017). "We investigated the differential expression of NCOA4 in cholangiocarcinoma tissues and paired non-cancerous tissues and found that NCOA4 expression was significantly lower in cholangiocarcinoma tissues than in normal tissues." (PMID 40788949, 2025). "At present, the effect and mechanism of action of NCOA4 in the malignant biological behavior of cholangiocarcinoma cells are not clear." (PMID 40788949, 2025).
Cognitive impairment (3 papers, 2022 to 2024). Abnormal cognition is characterized by deficits in thinking, reasoning, or remembering. "A series of Hu-antigen R (HuR) gain and loss experiments were used to examine cyclosporin A (CsA)-mediated translocation of HuR’s ability to improve MTX-induced cognitive impairment through NCOA4-mediated ferritinophagy in vitro and in vivo." (PMID 37950727, 2023). "Notably, the present assessment uncovered NCOA4-mediated ferritinophagy in MTX-induced cognitive impairment in mice and MTX-excited HT22 neuronal cells." (PMID 37950727, 2023). "Intervening in the translocation of HuR during CICI could mitigate neruoinflammation and neuronal apoptosis via NCOA4-mediated ferritinophagy and, thus, alleviate cognitive impairment in mice with CICI." (PMID 37950727, 2023). "Mediating the translocation of HuR during CICI could mitigate neruoinflammation and neuronal apoptosis via NCOA4-mediated ferritinophagy and, thus, alleviate cognitive impairment in mice with CICI." (PMID 37950727, 2023).
fibrosarcoma (3 papers, 2022 to 2026). A malignant mesenchymal fibroblastic neoplasm affecting the soft tissue and bone. "In addition, the mRNA level of NCOA4 in macrophages is reduced under hypoxic conditions, thereby preventing ferroptosis, while NCOA4 and FtMt levels in fibrosarcoma cells do not respond to a decrease in the oxygen level." (PMID 40083691, 2025).
HCMV infection (3 papers, 2021 to 2023). "During the HCMV infection, protein levels of NCOA4 and ferritinophagy are regulated, and Tiron and iron chelators ciclopirox olamine specifically protect cells from pUL38-deficient HCMV infection-induced cell death." (PMID 36653801, 2023). "Consistent with this, blockage of ferritinophagy by genetic ablation of NCOA4 prevented pUL38-deficient HCMV infection-induced cell death." (PMID 34062931, 2021).
Hearing Loss (3 papers, 2024 to 2025). "Our findings highlight the role of NCOA4-mediated ferritinophagy in the pathogenesis of cisplatin-induced ototoxicity and provide evidence for nuciferine as a promising protective agent for treating cisplatin-induced hearing loss." (PMID 38929153, 2024). "FOXO1 acts as a direct upstream regulator of NCOA4, inhibiting NCOA4‐mediated ferritinophagy and alleviating cisplatin‐induced SGN ferroptosis and hearing loss." (PMID 39206719, 2024).
iron overload (3 papers, 2022 to 2024). "To further elucidate the underlying mechanism by which SeNPs attenuate I/R-induced iron overload in TECs, we examined the protein levels of NCOA4, an identified ferritinophagy receptor, and ferritin." (PMID 39061070, 2024). "First, splenic iron overload has been associated with microcytic anemia in mice with systemic germline deletions of Ncoa4." (PMID 36290647, 2022).
ischemic stroke (3 papers, 2021 to 2025). A stroke disorder caused by obstruction of blood flow to the brain, due to thrombotic (local blood clot formation) or embolic (due to a blood clot or other material traveling from another site) event. "The Li group demonstrated that in ischemic stroke models, nuclear receptor coactivator 4 (NCOA4) drives ferroptosis by mediating ferritinophagy—a selective autophagic process that degrades ferritin, leading to free iron release and lipid peroxidation." (PMID 40529211, 2025). "Nuclear receptor coactivator 4 (NCOA4) facilitates ferritinophagy-mediated ferroptosis, and NCOA4 deletion protects neurons from ferritinophagy-mediated ferroptosis after ischemic stroke." (PMID 35264947, 2021).
lung adenocarcinoma (3 papers, 2017 to 2023). A carcinoma that arises from the lung and is characterized by the presence of malignant glandular epithelial cells. "Our study identified a novel m6A-related ferroptosis-associated six-gene signature (comprising SLC2A1, HERPUD1, EIF2S1, ACSL3, NCOA4, and CISD1) for predicting lung adenocarcinoma prognosis, yielding a useful prognostic biomarker and potential therapeutic target." (PMID 37072786, 2023).
lymph node metastasis (3 papers, 2019 to 2024). "While NCOA4::RET was associated with the tall-cell subtype, and presence of angio/lymphatic invasion and lymph node metastasis (p < 0.05)." (PMID 37188126, 2023). "NCOA4::RET rearrangements were statistically significantly associated with the tall cell subtype (p = 0.019) and angioinvasion (p = 0.001), lymphatic invasion (p = 0.003), lymph node metastasis (p= <0.001), extrathyroidal extension (p = 0.001) and extranodal extension (p = 0.013)." (PMID 37188126, 2023). "High expression levels of NCOA4::RET were found, but not significant in patients with the tall-cell subtype, extrathyroidal extension, lymph node metastasis and extranodal extension." (PMID 37188126, 2023).
oral cancer (3 papers, 2015 to 2025). "NCOA4 expression studies have reported its role in oral cancer and recognized as candidate serum markers for oral squamous cell carcinomas (OSCC)." (PMID 28324520, 2015). "Treatment with TFP significantly upregulated the expression levels of pro-ferroptotic proteins, such as FTH1 and NCOA4, while downregulating the expression levels of proteins that reverse ferroptosis, such as SLC7A11, GPX4 and Nrf2, in oral cancer cells." (PMID 39664583, 2024).
Parkinson disease (3 papers, 2024). A progressive degenerative disorder of the central nervous system characterized by loss of dopamine producing neurons in the substantia nigra and the presence of Lewy bodies in the substantia nigra and locus coeruleus. "Evidence generated in both PC cell and Parkinson disease (PD) models showed that FTH overexpression could yield negative feedback on ferritinophagy–ferroptosis axis via downregulating NCOA4 and microtubule‐associated protein 1 light chain 3 alpha." (PMID 38389491, 2024).
renal cell carcinoma (3 papers, 2012 to 2024). "Notably, the results showed that overexpression of NCOA4 was associated with renal cell carcinoma, the JAK-STAT pathway, Toll-like pathway and the NOD-like receptor pathway (|NES|> 1, p < 0.05, FDR < 0.25)." (PMID 34370716, 2021). "A recent gene expression profiling study identified NcoA4 as one of the genes upregulated in renal cell carcinoma but downregulated in late renal regeneration and repair." (PMID 22562579, 2012). "Since chronic renal regeneration and repair in individuals with polycystic kidney disease can lead to renal cell carcinoma, these results suggest that NcoA4 expression may be altered in the progression of this cancer." (PMID 22562579, 2012).
acute pancreatitis (2 papers, 2025). An acute inflammatory process that leads to necrosis of the pancreatic parenchyma. "However, the role of NCOA4-mediated ferroptosis in acute pancreatitis (AP) remains poorly understood." (PMID 41461917, 2025).
asthma (2 papers, 2022 to 2025). "By inhibiting ferroautophagy mediated by NCOA4 and averting ferroptosis, polydatin has been demonstrated to reduce asthma." (PMID 40667723, 2025). "Our study revealed that the model group presented elevated levels of NCOA4 and Beclin1 in lung tissue, whereas FTH1 and P62 expression were downregulated, suggesting that NCOA4‐mediated ferroautophagy is activated during asthma." (PMID 40667723, 2025). "Our results revealed that the expression of the autophagy-marked protein (LC-3) was enhanced in lung tissues of asthma mice and bronchial epithelial cells stimulated with IL-13, and the expression of autophagy related proteins (NCOA4, TFR1, and DMT-1) in these cells and tissues were also promoted." (PMID 35154576, 2022). "Furthermore, the expression of ferritinophagy-related proteins (NCOA4, ATG-5, and ATG-7) in the lung tissues was elevated upon the occurrence of asthma but was then repressed after the treatment of Ferr-1 and 3-MA." (PMID 35154576, 2022). "Of note, the impacts of Ferr-1 on the expression of NCOA4, TFR1, and DMT-1 in asthma were weak, partly suggesting that ferritinophagy was not the core regulatory mechanism by which Ferr-1 suppressed ferroptosis to ameliorate asthma." (PMID 35154576, 2022).
colitis (2 papers, 2024 to 2026). Inflammation of the colon. "Antioxidant Tempol and myeloid cell-targeted curcumin offer protection against colitis in myeloid NCOA4-deficient mice." (PMID 38798412, 2024). "CONCLUSIONS: This study provided evidence supporting that NCOA4-mediated ferritinophagy participates in modulating colitis-related ferroptosis in IECs, and suppressing ferritinophagy protects IECs and promotes colonic mucosal repair." (PMID 41821081, 2026). "Overexpression of myeloid cell-specific NCOA4 confers protection against Salmonella-induced colitis via upregulating NRF2 signaling." (PMID 38798412, 2024). "Activation of NRF2 protects myeloid NCOA4 knockout mice from Salmonella-induced colitis." (PMID 38798412, 2024).
COVID-19 (2 papers, 2021 to 2022). A disease caused by infection with severe acute respiratory syndrome coronavirus 2. "NCOA4-mediated ferritinophagy can be targeted to limit the ferroptosis and, therefore, prevent the multi-organ damage and severity in COVID-19 patients." (PMID 34977155, 2021). "The downregulation of NCOA4 may further provide the explanation for the expansion of CECs in peripheral blood of severe COVID-19 patients, as this protein was identified as a critical regulator of terminal erythroid differentiation." (PMID 35181867, 2022). "Therefore, we propose that NCOA4-mediated ferritinophagy can be targeted to limit the ferroptosis and prevent the multi-organ damage and severity in COVID-19 patients." (PMID 34977155, 2021).
endometriosis (2 papers, 2019 to 2025). The growth of functional endometrial tissue in anatomic sites outside the uterine body. "They intended to study the role of the intercellular levels of iron in the malignant transformation of endometriosis to specific subtypes of OCs by monitoring the expression of Nuclear Receptor Coactivator 4 (NCOA4)." (PMID 31013963, 2019).
fatty liver disease (2 papers, 2022 to 2024). A reversible condition wherein large vacuoles of triglyceride fat accumulate in liver cells via the process of steatosis. "It was shown that a high-fat diet (HFD) led to abnormal hepatic steatosis in mice as well as diminished iron levels, but that it also increased endoplasmic reticulum stress by accumulating p62 and disturbing the expression of NCOA4 and ferritin." (PMID 38961066, 2024). "Targeting NCOA4 also improved abnormal lipid metabolism, as an HFD reduced iron levels, resulting in abnormal hepatic steatosis and insulin resistance." (PMID 38961066, 2024).
glaucoma (2 papers, 2023 to 2025). Increased pressure in the eyeball due to obstruction of the outflow of aqueous humor. "However, the role of NCOA4 and ferritinophagy in glaucoma is unknown." (PMID 35933500, 2023).